MMP2 (matrix metallopeptidase 2)
Diseases named in the same sentence as MMP2 in open-access papers (continued):
Sharing a sentence is not in itself a finding about the gene and the disease.
ischemic stroke (continued). "Among the MMP family, MMP-2 also exerts proteolytic effects of endothelial cells only within several hours after experimental ischemic stroke, although other studies have shown no obvious increases in MMP-2 expression." (PMID 34804372, 2021). "Additionally, activated matrix metalloproteinases (MMPs), such as MMP-2, MMP-3, MMP-7, and MMP-9, induce BBB disruption in experimental ischemic stroke and severe inflammatory response following septic shock." (PMID 31547411, 2019). "However, there are currently no clear data on the dynamics of MMP-2 activity and secretion in relation to the ischemic focus during ischemic stroke." (PMID 37511788, 2023). "However, applying tPA after OGD treatment (ischemic stroke in vitro) led to the enhancement of MMP2 and 9 mRNA levels, but not their protein levels." (PMID 26881424, 2016). "The elevation of MMP-2 activity and the increase in vascular density after MSC treatment suggest that MSCs might help promote angiogenesis and lead to neurological improvement during the recovery phase after ischemic stroke." (PMID 26637168, 2015). "In addition to MMP-2/-3/-9, MMP-10 (stromelysin-2) may also play an active role in mediating BBB disruption during ischemic stroke." (PMID 23565108, 2013). "During ischemic stroke in mice, MMP-2 and MMP-9 have different roles in BBB disruption where MMP-2 does not contribute to acute tissue damage as evidenced by the absence of neuroprotection of MMP-2 knockouts." (PMID 33487119, 2021). "MMP-2, MMP-3 and cathepsin L showed a smaller AUC and had no predictive effects on ischemic stroke." (PMID 32982940, 2020). "Our finding that tPA does not amplify MMP-2 and MMP-9 in ICH potentially suggests that this drug is not activated by a parenchymal (i.e. extra-arterial) clot formation in the same way as it is activated by an intraluminal thrombus in ischemic stroke." (PMID 23408937, 2013).
periodontitis (66 papers, 2006 to 2025). An acute or chronic inflammatory process that affects the tissues that surround and support the teeth. "Several studies have demonstrated an association between MMP-2 and periodontitis, given that its activity is regulated by tissue inhibitors of matrix metalloproteinases (TIMPs), particularly TIMP-1, considered its main endogenous inhibitor." (PMID 41009326, 2025). "Among others, metalloproteinases for which the relationship between gene polymorphisms and the occurrence of periodontitis was evaluated are MMP-2 and MMP-9." (PMID 35454140, 2022). "Subjects with the genotype of MMP-2 −790 TT or T allele of MMP-2-790T/G, as compared to genotypes of GT + GG genotypes or G allele, were less susceptible to chronic periodontitis (OR = 0.50, 95% CI = 0.25–1.00 and OR = 0.52, 95% CI = 0.28–0.96, respectively)." (PMID 35454140, 2022). "In the past decade, several epidemiologic studies have been investigated the association of MMP-9 -1562C>T (rs3918242) and MMP-2 -753C>T (rs2285053) polymorphisms with susceptibility to periodontitis." (PMID 31497543, 2019). "The results were similar to MMP-3-1171 A5/A6 and MMP-2-753 C/T polymorphisms for periodontitis susceptibility." (PMID 27095260, 2016). "The MMP-9-1562C > T polymorphism showed a significant association with the risk of periodontitis among Caucasians and the chronic periodontitis/aggressive periodontitis subgroup, whereas MMP-2-753C > T polymorphism was significantly associated with periodontitis risk only among Asians." (PMID 35454140, 2022). "However, there is still a need for further research and screening of etiological relations of the MMP-2 and 9 genes functional polymorphisms with the susceptibility of periodontitis." (PMID 31497543, 2019). "Moreover, many molecular epidemiological studies has been conducted to investigate the association between MMP-3-1171 A5/A6, MMP-8-799 C/T, and MMP-2-753 C/T polymorphisms and periodontitis susceptibility." (PMID 27095260, 2016). "Besides, when stratified by the severity of CP and smoking, a similar distribution of all these MMP-2 variants was observed between periodontitis patients and controls." (PMID 27194818, 2016). "Saliva and sulcular levels of inflammatory biomarkers associated with chronic periodontitis could be investigated, such as free radicals, cytokines, matrix metalloproteinase (MMP)-2 and -8, tissue inhibitor of metalloproteinases (TIMP)-2 complex, or endothelin-1, for instance." (PMID 32218125, 2020). "Moreover, a significant association had not found between MMP-2 -753C>T polymorphism and periodontitis according to disease type and ethnicity, while we have found that MMP-2 -753C>T polymorphism was significantly associated with periodontitis risk only among Asians." (PMID 31497543, 2019). "The aim of the study was to investigate the effects of ω-3 PUFA on inflammation and on the expression of MMP-2 and -9 in a murine periodontitis model." (PMID 37378834, 2024). "Both in vitro and in vivo experiments confirmed the effectiveness of the nanoplatform for monitoring MMP-2 levels, showing great potential for periodontitis diagnosis." (PMID 39554809, 2024). "It has been shown that MMP-2 is crucial for the deterioration or turnover of soft connective tissue in chronic periodontitis." (PMID 38420070, 2024). "Among the Matrix metalloproteinases (MMPs), gingival Mmp2 expression was significantly upregulated by experimental periodontitis in both WT and Spock1-Tg mice." (PMID 38156070, 2023). "High concentrations of MMP-9 have been correlated with high gingival bleeding and intense dental motility and, together with MMP-2, it is responsible for a greater degradation of extracellular matrix constituents in periodontitis." (PMID 37026605, 2023). "The present study showed that MMP-2 levels in the gingiva were upregulated in both WT and Spock1-Tg mice, and active-MMP-2 levels in the gingiva were upregulated in Spock1-Tg mice and experimental periodontitis." (PMID 38156070, 2023).
periodontitis (continued). "In contrast, MMP-2 and 9 activities were decreased by administration of CsA despite of concomitant induction of experimental periodontitis." (PMID 38156070, 2023). "The study results identified a tremendous increase in the levels of MMP-8 and MMP-9, and a decrease in the level of MMP-2, in cases of periodontitis." (PMID 35626325, 2022). "Patients with severe periodontitis indicated a considerably higher level of salivary proMMP-2 and MMP-2 than healthy individuals." (PMID 32466129, 2020). "Patients with severe periodontitis indicated a considerably higher level of proMMP-2 and MMP-2 than healthy individuals." (PMID 32466129, 2020). "In the saliva of patients with periodontitis, increased concentrations of MMP-2, MMP-8 and MMP-9 were found in comparison to healthy patients." (PMID 33297580, 2020). "Other studies showed contradictory information, finding reduced levels of MMP-2 in patients with periodontitis." (PMID 31892956, 2019). "Nevertheless, the relationship between periodontitis and the gelatinolytic activity of MMP-2 in T2DM patients is contradictory." (PMID 31892956, 2019). "Previous studies on this topic have found higher levels of MMP-2 in saliva from patients with periodontitis." (PMID 31892956, 2019). "A representative zymography gel shows the gelatinase activity of WSS from periodontally healthy individuals, and patients with mild, moderate or severe periodontitis had increased activity of MMP-2 that corresponded with the severity of periodontal disease." (PMID 31892956, 2019). "In our meta-analysis, we accurately assessed the association between these MMP-2 -753C>T and MMP-9 -1562C>T polymorphisms and the risk of chronic/aggressive periodontitis by taking into account the effects of new published studies." (PMID 31497543, 2019). "In the present meta-analysis, we aggregated data from published studies to estimate genetic associations between MMP gene, namely MMP-2-753 C/T, MMP-3-1171 A5/A6, MMP-8-799 C/T, and MMP-9-1562 C/T polymorphisms, and periodontitis susceptibility." (PMID 27095260, 2016). "MMP-2 is secreted by gingival fibroblasts and the crevicular MMP-2 levels were seen to be lower in gingivitis and periodontitis conditions." (PMID 24490073, 2013). "We hypothesize that the supplementation with ω-3 PUFA, in ligature-induced periodontitis, could reduce periodontal destruction by decreasing inflammatory markers and with MMP-2 and MMP-9 activation as a mechanism of action." (PMID 37378834, 2024). "Moreover, in rat periodontitis, we used immunofluorescence and found that the expression of MMP2 and 9 was higher in both the periodontal zone and alveolar bone area after OMVs injection." (PMID 39475060, 2024). "MMP-2 was only severely activated in the chronic periodontitis group." (PMID 38420070, 2024). "Based on the systemic anti-inflammatory effects of ω-3 PUFA supplementation, it could be assumed that there is a positive host modulation of inflammatory bone destruction and of the MMP-2 and MMP-9 activity caused by periodontitis." (PMID 37378834, 2024). "Also, it decreased the serum expressions of TNFα and IL-2 and the tissue expression of MMP-2 and -9 in the periodontitis-induced model (p < 0.05)." (PMID 37378834, 2024). "Salivary MMP-2 activity and HbA1c were positively correlated with the severity of periodontitis." (PMID 37629193, 2023). "Clinical correlation studies suggest that high circulating MMP-2 levels may correlate with the severity of periodontitis in type 2 diabetes." (PMID 35281591, 2022). "It was suggested that MMP-2 T-790G, MMP-9 C-1562T, and TIMP-2 G-418C gene polymorphisms might be associated with periodontitis in the Taiwanese Han population." (PMID 35454140, 2022). "However, MMP-2-753C > T and MMP-9-1562C > T polymorphisms had an influence on the susceptibility of periodontitis by ethnicity." (PMID 35454140, 2022). "Hence, the research identified the fact that MMP-8, MMP-9, and MMP-2 biomarkers can aid in the diagnosis of periodontitis." (PMID 35626325, 2022).
periodontitis (continued). "Still, our study showed that they do have an important role, as well, in discrimination between the health vs periodontitis and gingivitis vs periodontitis groups (for MMP-2) and between the health vs gingivitis groups (for MMP-3) according to the ROC analysis." (PMID 33742017, 2021). "In addition, gelatinases such as gelatinase A (MMP-2) and gelatinase B (MMP-9) have been associated with periodontitis." (PMID 34833990, 2021). "Therefore, to clarify precise associations of MMP-2-753 C>T and MMP-9-1562C>T polymorphisms with chronic (CP) and aggressive (AgP) periodontitis, we performed a systematic review and meta-analysis." (PMID 31497543, 2019). "In the subgroup analyses, there was not a significant association between MMP-2 -753C>T polymorphism and periodontitis risk under all five genetic models in the CP and AgP groups." (PMID 31497543, 2019). "In short, when MMP-2 and -9 and transglutaminase-1–3 were analyzed in 22 patients with chronic periodontitis and healthy controls, transglutaminase-1 and 3 mRNA levels in chronic periodontitis patients were lower than those in healthy controls." (PMID 31336777, 2019). "Two functional polymorphisms in the matrix metalloproteinase-2 and -9 (MMP-2 and MMP-9) genes may contribute to periodontitis pathogenesis." (PMID 31497543, 2019). "Nevertheless, the relationship between uncontrolled glycemia and the gelatinolytic activity of MMP-2 in the saliva of T2DM patients with periodontitis is unknown." (PMID 31892956, 2019). "Taken together, these findings identify MMP-2 as a promising molecular market for periodontitis." (PMID 31892956, 2019). "In silico analysis demonstrates that HBPs may have a role in periodontal disease and can be used for identifying potential drug targets that include chemokines, CXCL12, and proteases, MMP-2 and -9, for regulating periodontitis." (PMID 26821679, 2016). "Finally, due to the overexpression of MMP-2 in the gingival tissue of periodontitis, the hydrogel depot was continuously degraded to release the NanoGSK cargo, and NanoGSK further spread and entered the PDLSCs to inhibit the inflammation-induced expression of PERK." (PMID 37896262, 2023). "Moreover, clinical correlation studies suggest that high circulating MMP-2 levels may correlate with the severity of periodontitis in T2DM." (PMID 31892956, 2019). "Thus, we performed the current systematic and meta-analysis of all available case-control studies to provide more precise estimation of the association of MMP-2 -753C>T (rs2285053) and MMP-9 -1562C>T (rs3918242) polymorphisms with chronic/aggressive periodontitis susceptibility." (PMID 31497543, 2019). "Therefore, the uncontrolled levels of glucose in T2DM could lead to an imbalance in MMP-2 activity in saliva, favoring the development of periodontitis." (PMID 31892956, 2019). "However, both MMP-2 -753C>T and MMP-9 -1562C>T polymorphisms might have influence on the susceptibility of periodontitis by ethnicity background." (PMID 31497543, 2019). "Therefore, both MMP-2 -753C>T and MMP-9 -1562C>T polymorphisms might have influence on the susceptibility of periodontitis by ethnicity background." (PMID 31497543, 2019). "However, MMP-2-753C>T and MMP-9-1562C>T polymorphisms might have influence on the susceptibility of periodontitis by ethnicity." (PMID 31497543, 2019). "In conclusion, this meta-analysis with published data suggested that the MMP-2-753 C/T, MMP-3-1171 A5/A6, and MMP-9-1562 C/T polymorphisms were associated with periodontitis susceptibility and there is lack of association between the MMP-8-799 C/T polymorphism and periodontitis." (PMID 27095260, 2016). "In this study, an increase in the enzymatic activity of MMP-2 was observed, as well as the expression of TMP-1 according to the severity of periodontitis, this increase being significant in severe periodontitis." (PMID 40406515, 2025).
periodontitis (continued). "Protein–protein interaction (PPI) network analysis identified ESR1, MMP2, MMP9, MMP13, and STAT1 as hub genes, highlighting their central role in EGCG-mediated modulation of periodontitis." (PMID 41009706, 2025). "Recent evidence highlights several molecular mediators involved in the pathogenesis of periodontitis namely estrogen receptor 1 (ESR1), matrix metalloproteinases (MMP2, MMP9, MMP13), and signal transducer and activator of transcription 1 (STAT1)." (PMID 41009706, 2025). "In this context, a significant increase in MMP-2 enzymatic activity as well as TMP-1 expression has been observed, according to the severity of periodontitis." (PMID 41009326, 2025). "By integrating these results with Gene Ontology, pathway, and disease enrichment analyses, it was determined that ESR1, MMP2, MMP9, MMP13, and STAT1 are potential key targets of EGCG in the context of periodontitis treatment." (PMID 41009706, 2025). "The authors concluded that several MMPs, particularly MMP-1, MMP-2, MMP-9, and MMP-13, are involved in gingival ECM degradation during periodontitis." (PMID 38474009, 2024). "Increased concentrations of MMP-2, MMP-7, and circulating MMP-8 have been found in patients with IPF while connective tissue deterioration in chronic periodontitis has been shown to be significantly influenced by these MMPs." (PMID 38420070, 2024). "Previous studies have demonstrated the relevance of MMP-2 and MMP-9 in periodontal diseases and increased MMP-13 activity in both murine model of periodontitis and human periodontitis." (PMID 38152410, 2023). "Gliclazide reduces oxidative stress, blocks PI3K signal transmission, and reduces matrix metalloproteinase 2 (MMP-2), cathepsin K, and RANKL levels in the rat periodontitis model." (PMID 34539410, 2021). "Salivary MMP-2 activity, HbA1c and TIMP-1 were positively correlated with the severity of periodontitis." (PMID 31892956, 2019). "Consistent with previous studies, our results indicate that SHI down-regulates IL-1, IL-6, TNF-α, MMP-2, MMP-9 and COX-2 expression in LPS-stimulated hPDLCs, thus indicating the anti-inflammatory potential of SHI in the treatment of periodontitis." (PMID 30392422, 2018). "Because type I collagen represents the bulk component of periodontal extracellular matrix, special attention has been paid to collagenases—particularly MMP-8 and MMP-13- and gelatinases—MMP-2, and MMP-9- in periodontitis." (PMID 28218665, 2017). "MMP-14 can activate MMP-8 and -13 in vitro, as well as MMP-2, and has been correlated in vivo with active MMP-13 in periodontitis sites." (PMID 28218665, 2017). "Cluster 3 was a subset with 14 genes that negatively correlated with MMP2 in healthy samples and positively correlated with MMP9, RANKL, and CTSK in only the periodontitis samples." (PMID 27486459, 2016). "And based on previous studies, dramatically elevated levels of MMP-1, MMP-2, MMP-3, MMP-8, and MMP-9 have been detected in gingival crevicular fluid, peri-implant sulcular fluid, and gingival tissue of periodontitis patients." (PMID 27194818, 2016). "Cluster 2 genes (n = 12) were positively correlated with the expression of MMP2 and CTSK in both health and periodontitis, as well as with MMP9 only in periodontitis." (PMID 27486459, 2016). "MMP-2 and MMP-9 have been demonstrated to regulate proteolytic degradation in periodontitis; the effects of PTL on the expression of MMP-2 and MMP-9 in hPDLCs were therefore investigated." (PMID 25610476, 2014). "Excessive production of MMP-2 and MMP-9 can lead to accelerated matrix degradation in pathological conditions such as periodontitis." (PMID 24819928, 2014). "The periodontium of untreated rats with experimental periodontitis showed marked immune-staining for COX-2, MMP-2, MMP-9, RANK-L, and RANK, compared to normal rats treated with saline alone." (PMID 24130702, 2013).